MAGEB6 (MAGE family member B6)
Synonyms: CT3.4; FLJ40242; MAGE-B6; MAGEB6A
Tractability: No criterion of Open Targets' tractability assessment is met for any kind of drug.
Gene: Protein-coding gene on chromosome X (26,192,440 to 26,195,646, forward strand). Ensembl gene ENSG00000176746.
Gene Ontology:
Molecular function: protein binding
Biological process: negative regulation of transcription by RNA polymerase II
Cellular component: nucleus
Homologues: Orthologues: rat Mageb6l1 (40% identical), rat Mageb4 (36% identical), mouse Mageb1 (35% identical), mouse Mageb2 (35% identical), mouse Mageb3 (35% identical), mouse Mageb6b1 (33% identical), mouse Mageb6b2 (33% identical), mouse Gm5071 (33% identical), rat Mageb6b1 (32% identical), rat Magebl1 (32% identical), zebrafish ndnl2 (17% identical), Drosophila melanogaster MAGE (14% identical). Paralogues in human: MAGEB6B (80% identical), MAGEB4 (41% identical), MAGEB1 (41% identical), MAGEB17 (37% identical), MAGEB2 (37% identical), MAGEB18 (36% identical), MAGEB3 (36% identical), MAGEB10 (33% identical), MAGEA10 (32% identical), MAGEB16 (32% identical), MAGEA11 (30% identical), MAGEA4 (30% identical), and 25 more.
Diseases named in the same sentence as MAGEB6 in open-access papers:
MAGEB6 is named in the same sentence as 8 diseases in open-access papers, as found by Europe PMC text mining. Sharing a sentence is not in itself a finding about the gene and the disease. The quoted sentences say what the papers report.
Azoospermia (1 paper, 2022). Absence of any measurable level of sperm,whereby spermatozoa cannot be observed even after centrifugation of the semen pellet. "We also focused attention on genes from the MAGE family, which have been described in the development of malignances, that is, the MAGEB6 gene (locus Xp21.3) but have never been reported in azoospermia." (PMID 36017582, 2022).
liver cancer (1 paper, 2024). An epithelial or non-epithelial malignant neoplasm that arises from the liver. "The model of SPP1 combined with centromere protein A (CENPA), melanoma-associated antigen family member B6 (MAGEB6), and homeobox D9 (HOXD9) can predict the overall survival in liver cancer patients." (PMID 38374893, 2024).
cancer (2 papers, 2018 to 2021). A tumor composed of atypical neoplastic, often pleomorphic cells that invade other tissues. "While extensive interactions between MAGE family genes such as MAGEA9, MAGE9B, MAGEB6 and MAGEC1 correspond to the cancer subtypes BLCA, HNSC and LUSC, interactions between Zinc fingers C2H2-type proteins in the downregulated components characterized COAD and READ cancer subtypes." (PMID 34728699, 2021).
tumor (2 papers, 2022 to 2024). "First, we found multiple MAGE family proteins (e.g., MAGEC2, MAGEB2, MAGEC1, MAGEB6) with a gene expression profile similar to those in clinical trials (MAGEA1, MAGEA4), which have been reported to be tumor specific." (PMID 39515334, 2024). "Eight genes were significantly mutated only when both C1 and C2 clusters were combined in a single analysis, while a further two genes (MAGEB6 and DNAJB1) were categorised as SMGs in the C1 cluster but were no longer significant when C2 tumours were included in the analysis." (PMID 36207323, 2022).
MAGEB6 also shares sentences with these, for which no sentence is quoted: head and neck squamous cell carcinoma (2 papers); colon cancer (1); Infertility (1); Lung squamous cell carcinoma (1).